PTH (parathyroid hormone)
Diseases named in the same sentence as PTH in open-access papers (continued):
Sharing a sentence is not in itself a finding about the gene and the disease.
hyperparathyroidism (continued). "Serum calcium and PTH were 2.9 mmol/L and 256.5 pg/ml right after surgery, and 2.78 mmol/L and 294.3 pg/ml at 3 months, respectively, suggesting that hyperparathyroidism was not completely relieved." (PMID 37795364, 2023). "Another report documented a patient with hyperparathyroidism who underwent exploration of the neck and excision of three and half parathyroid glands, all were normal, and PTH level was not lowered." (PMID 36407056, 2022). "There is no consensus regarding a PTH level which clearly defines the presence of persistent post-transplant hyperparathyroidism." (PMID 36672533, 2022). "Although IL-6 is secreted from normal parathyroid tissue and with PTH in hyperparathyroidism, the negative correlation of IL-6 with PTH in our study can be explained by slight increases in Ca levels." (PMID 36161625, 2022). "Cinacalcet, a calcimimetic, is considered in cases of significant hyperparathyroidism (PTH > 300 pg/mL) and thus was not indicated in this patient." (PMID 35039083, 2022). "Therefore, specific and optimized design for PTH removal is necessary for CKD patients, especially for the patients with hyperparathyroidism disease." (PMID 34202416, 2021). "In such a case, high PTH values are indicative for vitamin D resistance, assuming that dietary calcium and phosphate intake are adequate and a differential diagnosis of hyperparathyroidism has been ruled out." (PMID 33897704, 2021). "PTH measurement is considered of clinical utility in dogs affected with any stage of CKD, in order to determine if hyperparathyroidism is present, since RHPT could occur at different stages of CKD, and also in the absence of hyperphosphatemia." (PMID 33348538, 2020). "None of the four remaining patients developed hyperparathyroidism, serum PTH concentrations increasing in all of them but within the normal range." (PMID 32133333, 2020). "The intraoperative PTH levels normalised in all patients after the excision of enlarged glands and there was no persistent hyperparathyroidism." (PMID 32606444, 2020). "Screening for hyperparathyroidism with annual biochemical evaluation of calcium and PTH is recommended starting at the age of 8, which is the age at which the earliest symptomatic patient with PHPT has been described (asymptomatic hyperparathyroidism has been observed as early as age 4)." (PMID 31263451, 2019). "While parathyroid hormone (PTH) itself is a vasodilator, perhaps as the result of increased prostaglandin production, hyperparathyroidism in end stage renal disease is thought to produce hypertension by encouraging entry of calcium into the smooth muscle cells vascular walls." (PMID 29751781, 2018). "There is no consensus on the acceptable PTH target level that defines refractory hyperparathyroidism." (PMID 30123263, 2018). "If intracystic PTH levels are high and the patient has no sign of hyperparathyroidism, including normal plasma and calcium levels, yearly surveillance is advisable." (PMID 29183364, 2017). "Hyperparathyroidism is frequently listed as a cause for ESA resistance; however, we did not identify any association with PTH level." (PMID 29178879, 2017). "In this case neither the clinical symptoms nor the serum calcium and parathyroid hormone levels indicated severe hyperparathyroidism as usually seen in PCA." (PMID 29354025, 2017). "The phenotype suggests a marked impairment of Ca2+o-dependent negative feedback on PTH secretion with attendant hyperparathyroidism and PTH-dependent bone resorption." (PMID 28018229, 2016). "Calcinosis often occurs, however, in the absence of hyperparathyroidism, an observation that highlights the importance of PTH-independent ectopic mineralization-promoting factors in the generation of an elevated Ca x P product." (PMID 27683096, 2016). "As it pertains to hyperparathyroidism, our study did not demonstrate any change in mean plasma PTH levels but still demonstrated a significant attenuation in BMD loss in the nocturnal HD cohort." (PMID 27252880, 2016).
hyperparathyroidism (continued). "For sake of differential diagnosis with hyperparathyroidism-jaw tumor (HPT-JT) syndrome, several laboratory analyses, which included serum parathyroid hormone (PTH), phosphate levels, calcium levels, and alkaline phosphatase (ALP) activity, were undertaken accordingly." (PMID 26945411, 2016). "It has been known that several cases also developed hyperparathyroidism after acute renal failure without hemodialysis because of skeletal resistance to parathyroid hormone." (PMID 27462491, 2016). "We explored the relation between changes in PTH during treatment with vitamin D analogs and changes in NT-proBNP, and found that the degree of suppression of hyperparathyroidism during 16 weeks of treatment did not influence changes in NT-proBNP." (PMID 25112372, 2014). "Of note, 26(32.5%) diabetic cases had 2ry hyperparathyroidism and 54(67.5%) cases had normal parathyroid hormone level; meanwhile, none of the control group had 2ry hyperparathyroidism (P < 0.01)." (PMID 24228797, 2013). "PIN1 was essential for KSRP mediated PTH mRNA decay such that mice lacking Pin1 expressed elevated serum PTH levels, mimicking hyperparathyroidism." (PMID 23675491, 2013). "The patient neither had clinical symptoms or signs of hyperparathyroidism nor did the laboratory data other than the increased intact PTH level suggest hyperparathyroidism." (PMID 23710381, 2013). "Other than the elevated parathyroid hormone level, there was no clinical or laboratory evidence to substantiate the diagnosis of recurrent hyperparathyroidism." (PMID 23710381, 2013). "Furthermore, Ca, P, and PTH levels are in normal limits in GCRG, and it can be differentiated form Brown tumor of hyperparathyroidism." (PMID 23585980, 2013). "Hyperparathyroidism (HPT) is a common endocrine disorder with incompletely understood etiology, characterized by enlarged hyperactive parathyroid glands and increased serum concentrations of parathyroid hormone and ionized calcium." (PMID 18044981, 2007). "Additionally, PTH was only minimally elevated in 8‐month PSEN1 KI mice and not changed in younger PSEN1 KI mice, ruling out hyperparathyroidism as a likely cause of low bone mass." (PMID 41496612, 2026). "In addition, lithium-treated patients display a high proportion of elevated PTH (8.6%) and calcium levels (24.1%), as well as a higher prevalence of hyperparathyroidism (18%) in comparison with subjects who had never been exposed to lithium." (PMID 40182382, 2025). "Since the increased PTH levels in our patient are accompanied by a rise in the 1,25-dihydroxy vitamin D levels, calcitriol is not an effective therapeutic option for burosumab-induced hyperparathyroidism." (PMID 40922882, 2025). "The spectrum of hyperparathyroidism with high serum calcium and yet normal PTH levels is not extensively defined and may involve calcium-sensing receptor variations." (PMID 40709988, 2025). "Furthermore, elevated perioperative PTH levels in cases with recent normal outpatient levels do not necessarily imply hyperparathyroidism in those undergoing thyroidectomy." (PMID 39831132, 2025). "The observed capacity of the Aβ42-neutralizing antibody aducanumab to mitigate PTH hypersecretion in vivo in the murine models and ex vivo in human parathyroid tissue presents an intriguing possibility for repurposing an FDA-approved agent for medical management of hyperparathyroidism." (PMID 40492090, 2025). "The true incidence of lithium-induced hyperparathyroidism remains unclear, as PTH levels are not routinely assessed in these patients, and many cases are asymptomatic." (PMID 40182382, 2025). "For these reasons, current Kidney Disease Improving Global Outcomes (KDIGO) guidelines suggest to not transplant patients with severe hyperparathyroidism until they are adequately treated, with PTH levels in the range of approximately 2–9 times the upper normal limit for the assay." (PMID 38384325, 2024).
hyperparathyroidism (continued). "Thus, the timing and frequency of the PTH and 25OHD assessments differed between the patients, and PTH was measured more frequently in patients who were found to have developed hyperparathyroidism than in patients without hyperparathyroidism." (PMID 39141058, 2024). "However, the specific relationship between PTH and glucose metabolism is still controversial in individuals without hyperparathyroidism." (PMID 38590929, 2024). "A mutated RGS14 that cannot effectively block the inhibitory action of PTH on NaPi-2a could produce biochemical disturbances of hyperparathyroidism without increased serum PTH levels." (PMID 38731904, 2024). "Persistence of hyperparathyroidism, mostly defined as parathyroid hormone levels at least two times above normal although no consensus has been reached, within 12 months of kidney transplantation is referred as post-transplant hyperparathyroidism." (PMID 38410685, 2024). "Therefore, for patients with refractory hyperparathyroidism, PTH level should not be too low when surgical resection is performed clinically." (PMID 37102663, 2023). "After removal of culprit lesion in those 12 participants, they had successful recovery of PTH after 6 months of surgery, without evidence of persistent or recurred hyperparathyroidism, which followed the clinical course of single gland disease rather than multi gland disease." (PMID 35487946, 2022). "Parathyroid carcinoma (PCa) is a rare endocrine disease representing <1% of the parathyroid gland’s tumors, which may led to elevated parathyroid hormone (PTH) secretion, hypercalcemic crisis, bone disorders, renal failure and a consequent fatal hyperparathyroidism." (PMID 35586620, 2022). "However, renal hypophosphatemia did not appear to be driven by hyperparathyroidism, since PTH did not correlate with phosphate-SDS or TmP/GFR-SDS." (PMID 35137195, 2022). "Another study done with a control group suggested a contradicting result, in which the pathological group with an endocrine disorder (hyperparathyroidism) showed no significant rise of calcium in the CSF as compared to the plasma, and there was a weak link of calcium with PTH in the CSF." (PMID 33604214, 2021). "Hyperparathyroidism was also ruled out by decreased level of PTH." (PMID 35154010, 2021). "Yet, they did not demonstrate hyperparathyroidism, defined as PTH >65pg/mL." (PMID 34624060, 2021). "Even though atherosclerosis is associated with many risk factors such as aging, hypertension, diabetes, hyperphosphatemia, hyperparathyroidism, and hypervitaminosis D, our prospective animal study did not control for many factors such as parathyroid hormone and other factors." (PMID 33976243, 2021). "However, the plasma PTH level in Vdr-KO rats was not reduced (a significant trend, with t = 2.252, df = 5.002, p = 0.074), suggesting hyperparathyroidism in these rats." (PMID 32231239, 2020). "Furthermore, somatostatin analogs have been tested in the treatment of hyperparathyroidism alongside surgery without an apparent effect on the patients’ serum calcium or PTH levels." (PMID 31336364, 2019). "A feedback of FGF23 on PTH production may not be present in advanced hyperparathyroidism due to resistance to the action of FGF23." (PMID 30086150, 2018). "In present investigation, four in 80 participants had hyperparathyroidism (serum PTH > 65 pg/mL), which could not explain why serum PTH was increased in participants with low level of serum vitamin D [25(OH)D]." (PMID 28473985, 2017). "Also, two ratios of (iPTH – 1-84 PTH/ iPTH) and (iPTH – 1-84 PTH/1-84 PTH) had no enough power to predict hyperparathyroidism (AUC of 0.630 for both)." (PMID 28975108, 2017). "We hypothesized that a longer follow-up may increase the number of patients that correct hyperparathyroidism because after supplementation the time it takes to normalize PTH is not set." (PMID 27699068, 2016). "In the present study, the patient’s PTH level was not high and hyperparathyroidism could be ruled out." (PMID 25435965, 2015).
hyperparathyroidism (continued). "Also, most of the patients were classified as having a relatively mild hyperparathyroidism, which is usually accompanied by lower serum calcium and PTH levels, unlike other reports were hyperparathyroidism was detected in more advanced stages." (PMID 25886602, 2015). "Although these anions from environmental and dietary sources negatively regulate PTH levels and are unlikely to account for the development of hyperparathyroidism, our results unveil the complex interaction between PTH regulation and other unknown factors." (PMID 25514572, 2014). "The results from this study may provide some insights into to non-classical regulatory mechanisms of PTH secretion and potential contributing factors to hyperparathyroidism." (PMID 25514572, 2014). "Therefore, other than a high PTH level there were no clinical signs or symptoms or laboratory data to support a diagnosis of recurrent hyperparathyroidism." (PMID 23710381, 2013). "Recently, we revisited the issue of T-cell-dependent PTH activity and confirmed that T cells play an essential permissive role in hyperparathyroidism as cPTH failed to induce osteoclast formation, bone resorption, and cortical bone loss in nude mice lacking T cells." (PMID 24278766, 2013). "In addition, 26(32.5%) diabetic cases had 2ry hyperparathyroidism and 54(67.5%) cases had normal parathyroid hormone level; meanwhile, none of the control group had 2ry hyperparathyroidism (P < 0.01)." (PMID 24228797, 2013). "Hyperparathyroidism may be ruled out on the basis of serum calcium, phosphorus and parathyroid hormone levels." (PMID 24223633, 2013). "However, in the absence of available PTH levels, it was not possible to identify a control group that would have had the same severity of hyperparathyroidism and did not receive cinacalcet." (PMID 23642012, 2013). "In particular, among the most common laboratory tests ordered are ones for vitamin B12 levels (to rule out subacute combined degeneration), parathyroid hormone levels (to rule out hyperparathyroidism), and serum protein electrophoresis with immunofixation (to rule out multiple myeloma or MGUS)." (PMID 20809955, 2010). "Although our dataset did not include the direct indicators for hyperparathyroidism, such as intact parathyroid hormone or alkaline phosphatase, it may be possible that hyperparathyroidism did not serve as a confounding factor influencing the association between the ERI and all-cause mortality." (PMID 40283642, 2025). "Disorders of excess PTH secretion (hyperparathyroidism) can be primary, for instance because of autonomous secretion by a tumour in one of the four glands, or secondary to a low calcium and/or low vitamin D. In primary hyperparathyroidism, the calcium is high and the PTH is not suppressed." (PMID 37139470, 2023). "In the current study, patients with severe inflammation or hyperparathyroidism were not included (the mean hCRP and int-PTH levels were 0.29±1.23 mg/dL and 148 ± 121 pg/mL, respectively), which may explain the discrepancy between this study and previous studies." (PMID 26933949, 2016). "Since in transplanted patients, tertiary hyperparathyroidism is relatively common, in order to rule out the possibility that hyperparathyroidism might influence the correlation between PTH or 25D with fibrosis, we excluded patients with tertiary hyperparathyroidism (n = 13)." (PMID 28036331, 2016). "Factors contributing to the hyperparathyroidism in PHP may include frequent small unrecognized declines in the serum calcium concentration in addition to a reduction in 1,25−dihydroxy−vitamin D. Other suggested explanations include secretion of an abnormal PTH, or abnormal metabolism of PTH." (PMID 21274302, 2009). "The prevalence of lithium-induced hyperparathyroidism (Li-HPP) has not been well established due to its asymptomatic nature in most cases and the lack of routine measurement of PTH and calcium levels in these patients." (PMID 40182382, 2025).
hyperparathyroidism (continued). "Hence, current guidelines state that it is reasonable to reserve the use of calcitriol and active vitamin D compounds for patients with advanced CKD and severe and progressive hyperparathyroidism although more targeted PTH control during non-dialysis-CKD period may influence outcomes during HD." (PMID 38817914, 2024). "The Current Management of Secondary Hyperparathyroidism, a Multi-Center Observational Study (COSMOS) study showed the survival benefit with increase of PTH level in HD patients with baseline PTH < 168 pg/mL, but not those with decrease of PTH." (PMID 30290781, 2018). "Because PTH is not reported in many cohort studies, the exact percentage of ADTKD-HNF1β patients suffering from hyperparathyroidism is unknown." (PMID 35554666, 2022). "In contrast, physicians might have expected that patients in the IV group (high serum intact PTH and ALP levels, low serum calcium) did not suffer from irreversible hyperparathyroidism, and therefore were likely to respond to an intravenous VDRA pulse due to their relatively short dialysis vintage." (PMID 34787531, 2021). "But as hyperparathyroidism may be multifactorial in HIV-infected patients and TDF may have effects on other factors that directly increase PTH, vitamin D supplementation could be not enough to normalize PTH but to improve the levels as we have seen in the present study." (PMID 27699068, 2016).